IL6 (interleukin 6)
Diseases named in the same sentence as IL6 in open-access papers (continued):
Sharing a sentence is not in itself a finding about the gene and the disease.
COVID-19 (continued). "Laboratory abnormalities of most affected COVID-19 patients include neutrophilia, lymphopenia, increased C- reactive protein, and pro-inflammatory cytokines such as interleukin 6 (IL-6), IL-2, IL-7 and tumor necrosis factor-alpha (TNFα) among others." (PMID 34072088, 2021). "Actually, serum IL-6 level has been widely accepted as prognostic marker in COVID-19 as its elevation is the most frequently reported." (PMID 33859644, 2021). "Among the therapeutic options for COVID-19, Tocilizumab, an inhibitor of the pro-inflammatory interleukin-6 (IL-6) was used in COVID-19 patients with elevated inflammatory markers and rapidly escalating oxygen requirements." (PMID 35095900, 2021). "The so-called COVID-19–related cytokine storm is a potentially fatal immune reaction induced by hyper-production -activation of T cells, during which a strong induction of IL-6 secretion is observed." (PMID 33981314, 2021). "Cytokines, such as IL-6 and TNF-a, found in the serum of patients with COVID-19, impede the mitochondrial OXPHOS pathway, causing a decrease in the ATP production and an abnormal mt-ROS production, which support cellular diseases and ageing." (PMID 34577851, 2021). "COVID-19 initiates an immune response over-activity leading to release of pro-inflammatory cytokines, particularly interleukin-6 (IL-6), which leads to overt thyroid dysfunction by disruption of desiodases and thyroid transport proteins." (PMID 33784355, 2021). "Since IL-6 is a pivotal biomarker in COVID-19 disease progression, we examined IL-6 levels in HCoV-OC43-infected and -uninfected HCT-8 and MRC-5 cells." (PMID 34483914, 2021). "IL-6 is a critical component in the initiation of cytokine storm/hyperinflammatory syndrome that represents the deadly complication of COVID-19." (PMID 34207220, 2021). "Our study supports previous studies showing that high levels of IL-6 lead to poor outcomes for COVID-19 patients." (PMID 34790978, 2021). "Early studies suggested beneficial effects of the IL-6 inhibitor tocilizumab and the IL-1 receptor antagonist anakinra in severely ill COVID-19 patients." (PMID 34769508, 2021). "There were three molecular functions with IL6 involvement among the first five molecular functions in which the junction targets of COVID-19 and LHQW were involved (P ≤ 0.05)." (PMID 34731090, 2021). "Considering only the COVID-19 positive patients, we found that those with higher concentrations of IL-10 (>200 ng/L) or IL-6 (>100 ng/L) had higher concentrations of CCL2, galectin-3, and PON1 concentrations." (PMID 34205807, 2021). "Critical COVID-19 is distinguished by very high levels of IL-1β and T lymphocyte activation (including IL-7), whereas septic shock displays higher levels of IL-6, IL-8 and a more significant myeloid response (including TREM-1 and IL-1ra)." (PMID 35111777, 2021). "For example, intensive care unit COVID-19 patients have the highest concentrations of IL-1β, IL-6, and IL-6 to IL-10 ratio." (PMID 34578898, 2021). "In this regard, the level of IL-6 showed a considerable correlation with the severity of COVID-19, and the measure of this cytokine can be used as an important factor in predicting disease severity." (PMID 34068970, 2021). "Although the mechanism is not fully understood, MHC II downregulation was also demonstrated in monocytes and B cells from COVID-19 patients and its expression was partially restored by using an inhibitor targeting IL-6, a major driver of COVID-19 pathology." (PMID 34198973, 2021). "The severity of COVID-19 can be assessed by detecting inflammatory biomarkers, including high levels of IL-6 and plasma CRP, and the release of these factors is closely related to ARDS." (PMID 34955842, 2021). "In our study, many of these cytokines and chemokines, especially CCL2, CXCL10, and IL6, were found to be significantly overexpressed in COVID-19 patients." (PMID 35145507, 2021).
COVID-19 (continued). "Monoclonal antibodies such as tocilizumab (TCZ) and sarilumab both compete with IL-6 for IL-6 receptor sites and effectively regulate cytokine storm in severe cases and have been used in several clinical trials to treat patients with COVID-19." (PMID 33946736, 2021). "Evidence suggests that both dexamethasone and anti-IL-6 antibodies can improve COVID-19 survival and mortality rates." (PMID 35003063, 2021). "Considering the importance of IL-6 in COVID-19, it is rational to identify the genes and pathways regulated by IL-6." (PMID 33520118, 2021). "Recently research indicated that suspected sHLH related to COVID-19 received IL-6 antagonistic therapy and Anakinra (recombinant soluble receptor antagonist of IL-1β and IL-1α)." (PMID 33926377, 2021). "Multiple studies have shown that there was a strong correlation between serum IL-6 levels and respiratory failure in patients with COVID-19." (PMID 37287491, 2021). "Cardiovascular diseases in COVID-19 patients involves IL-6, ACE2, and angiotensin as the critical mediators that drive the pathological process." (PMID 33995078, 2021). "The coronavirus disease 2019 (COVID-19) is associated with cytokine dysregulation, increased IL-1β, tumor necrosis factor (TNF) and IL-6 release with hyperinflammation and risk of CSS." (PMID 33562758, 2021). "In the setting of a more severe COVID-19 illness, these pro-inflammatory cytokines IL-6, IL-2 and TNF-α are released resulting in a cytokine release syndrome, and trigger myocardial inflammation." (PMID 33034203, 2021). "In trans-presentation, IL-6-mIL-6R complex was presented by specialized dendritic cells on their membrane to Th17 cells expressing gp130, which explained how excessive IL-6 induced overactivation of Th17 cells in COVID-19 patients." (PMID 34766001, 2021). "Our results are in favor of the suggested involvement of neutrophils networks, IL-6 production, along with different organ/tissue involvement in systemic oxidative stress in COVID-19." (PMID 34356359, 2021). "As seen in the whole blood transcriptome analysis, leukocytes from COVID-19 patients also demonstrated elevated IL-1β and IL-6 module activity compared with controls, and once again this distinction was not seen in IL1A, IL1B, and IL6 gene expression." (PMID 33319166, 2021). "Severe COVID-19 is characterized by high levels of pro-inflammatory cytokines (IL-1, IL-6 and TNF-α) and ferritin, activating endothelial cells of lung blood vessels." (PMID 34359355, 2021). "This study integrated liver function data and ILs data in patients with COVID-19 and found that liver injury and two ILs, interleukin-2 receptor (IL-2R) and interleukin-6 (IL-6), were closely related to the prognosis of patients with COVID-19." (PMID 34970527, 2021). "Based on these results, we postulated that COVID-19 patients with increased IL-6 levels should be expeditiously identified and receive effective intervention." (PMID 34123873, 2021). "Angiotensin II activates JAK/STAT and the NFκB pathway in COVID-19 patients, increasing IL-6 production." (PMID 33935717, 2021). "The same was true for the chemokine Interferon-y protein 10 (IP-10) which is only transiently increased in the common influenza, while in COVID-19 patients its expression remains constant and, as with IL-6 and IL-10, is correlated with disease severity." (PMID 34072088, 2021). "Instead, IL-6, a cytokine that was described as involved in the typical COVID-19-related “cytokine storm”, was lower in all PC patients who had similar levels as the healthy subjects." (PMID 34944747, 2021). "One of these drugs is tocilizumab, an immunoglobulin G1(IgG1) subclass antibody that inhibits the IL-6 receptor and that was tested in COVID-19 patients with elevated IL-6 levels, has exhibited several beneficial effects." (PMID 34360616, 2021). "The current study focused on the levels and prognosis of seven indicators including oxygen, lymphocytes, albumin, leukocyte, CRP, IL-6, and D-dimer in COVID-19 patients." (PMID 34778296, 2021).
COVID-19 (continued). "One of the controversial issues of immunomodulator therapy is the administration of interleukin-6, such as Tocilizumab, in COVID-19 management." (PMID 34809657, 2021). "Cytokine blocking strategy (blockade of IL-1 and IL-6) was the most often chosen treatment option for patients with clinically severe COVID-19 reaching support of 83.6% and 85.5% respondents, respectively, for use in stage III." (PMID 33683393, 2021). "Severe COVID-19 patients have been shown to exhibit higher levels of IL-2, IL-6, IL-10, IL-1, GSCF, MCP-1, TNF-α, and MIP1A." (PMID 35250966, 2021). "IL6 is one of the cytokines shown to be elevated in COVID-19 patients, and it is also a vital cytokine needed to mount a preliminary immune response against virus infection." (PMID 34513735, 2021). "Studies in Wuhan, China, showed that patients with severe COVID-19 symptoms had higher levels of IL-6 and other inflammatory cytokines in their blood samples." (PMID 34947872, 2021). "In patients with COVID-19, an increased IL-6/AAT ratio was correlated with poor prognosis, while a reduced IL-6/AAT ratio was associated with clinical resolution." (PMID 34066804, 2021). "Plasma level of Interleukin-6 (IL-6) reported in severe cases of COVID-19, as well as in “hypo” and hyperinflammatory processes in acute respiratory distress syndrome (ARDS)." (PMID 34066091, 2021). "One study preprint reported that monoclonal antibodies against IL-6 improved survival and other clinical outcomes in hospitalised COVID-19 patients with hypoxia and systemic inflammation." (PMID 34000622, 2021). "Although there is a decrease in CD4 and CD8 lymphocyte cells and NK cells in the most severe cases of COVID-19, hyperactive circulating monocytes continue to produce proinflammatory cytokines, such as TNFα and IL-6." (PMID 33791232, 2021). "Blockade of IL-6 signalling, using Tocilizumab, has also been investigated in COVID-19, and demonstrated patient discharge from the hospital within 28 days." (PMID 35593707, 2021). "For example, COVID-19 is linked to cytokine release syndrome (CRS), and the pathogenesis of CRS is associated with IL-6-mediated production of hyperinflammatory cytokines and plasminogen activator inhibitor-1 (PAI-1)." (PMID 34454610, 2021). "The data showed that, once the PP and NNp groups were compared with the PPh, IL-6 and eGFR were also indicative of the grade of severity of different diseases (NNp) but also revealed common patterns that make COVID-19 ((p > 0.05)." (PMID 34576798, 2021). "Plasma proteomics profiling also identified IL-6 among the most perturbed proteins in COVID-19 patients and marked as an indicator of disease severity." (PMID 33078369, 2021). "TNF-α, IL-1 and IL-6 are the main inflammatory cytokines derived from adipose tissue and increased IL-6 levels are predictive of COVID-19 severity and mortality." (PMID 33816341, 2021). "The results showed that both IL-6 (p = 0.005) and IL-17 (p = 0.02) were significantly higher in COVID-19 oral samples than in controls." (PMID 34248910, 2021). "Compared with other studies, the predictive effect of age, panting, and lymphopenia has been described in previous reports, while the main feature of this study is the analysis of the prognostic value of IL-6 in severe COVID-19 patients for the first time." (PMID 33731184, 2021). "No study has investigated the association between the use of corticosteroids and other immunomodulatory therapies such as anti-IL-6 Tocilizumab and secondary invasive Aspergillosis in COVID-19 patients." (PMID 34199528, 2021). "Although our sample size was limited for blood group A COVID-19 patients (n = 111 samples), they had the highest IL-6 levels." (PMID 34571942, 2021). "Searching for monoclonal antibodies of IL-6 or IL-6R will be critical for development of COVID-19 therapeutic drugs." (PMID 37287491, 2021).
COVID-19 (continued). "On the other hand, the cytokine storm that occurs in patients with severe COVID-19, confirmed by the high serum levels of IL-6 in our patients of the Ist wave, contributes to the lymphocyte exhaustion." (PMID 34211953, 2021). "Once the large majority of our patients were treated with drugs that are now known to be ineffective in COVID-19, we believe this IL-6 kinetics reflects the pathophysiology of disease accurately." (PMID 33679753, 2021). "In summary, D-dimer, CRP, ferritin, cardiac troponin I, IL-6 are predictive laboratory markers and can largely determine the clinical course of COVID-19, in particular the prognosis of critically ill COVID-19 patients." (PMID 34262116, 2021). "In 2020, IL-1β, IL-6, and other proteins were found to be correlated with pulmonary inflammation with extensive lung involvement, as seen in COVID-19 patients." (PMID 34017253, 2021). "For example, it was discovered that when a high dose of IV vitamin C was given to critically ill COVID-19 patients, their levels of interleukin-6 (IL-6) were lower than the placebo group." (PMID 34947872, 2021). "From previous studies on SARS-CoV, we predict that high IL-6 expression during COVID-19 cytokine storm is mediated by NF-κB." (PMID 34630379, 2021). "Another potentially important factor involved in QTC prolongation in COVID-19 is the high-grade systemic inflammation which characterize the diseases, frequently a real ‘cytokine storm’ in which IL-6 seems to play a pivotal role." (PMID 32615807, 2021). "Our data, therefore, link the prominent role of the IL-6 response in COVID-19 to coagulation and the complement cascade." (PMID 34139154, 2021). "On the other hand, patients receiving TOC and non-TOC SOC therapies seem to be well balanced with regard to comorbidities and co-medications for COVID-19, and undoubtedly its advantage is the assessment of baseline serum IL-6 concentration." (PMID 33918563, 2021). "In the clinical treatment of patients with COVID-19, Xuebijing Injection mainly inhibited IL6, TNF-α, MCP1, mip2, and IL10 to inhibit inflammatory response." (PMID 34335247, 2021). "This shows that aging profoundly affects COVID-19-related IL-6 signals, even in the early stage of SARS-CoV-2 infection." (PMID 34471088, 2021). "The risk of unfavourable outcome was directly proportional to the degree of delay, with the 23.3% diabetic patients with COVID-19 who died in this category, despite the initiation of IL-6 antagonist treatment." (PMID 34201473, 2021). "This was theorized to be related to the activation of the IL-6/JAK/STAT3 pathway in the tumor microenvironment of bladder cancer patients, which further exacerbates the inflammation caused by COVID-19." (PMID 34063231, 2021). "We propose that blockade therapy of IL-6 and IL-2R will be a promising treatment strategy for patients with COVID-19." (PMID 34970527, 2021). "In COVID-19 patients with moderate disease severity, higher levels of IL-6 and D-dimer with increased frequency of pulmonary infiltration were associated with severe headache." (PMID 34384355, 2021). "It is worth noting that IL-6 was the most reported cytokine among COVID-19 patients included in the study, and a total of seventeen IL-6 relevant studies were included." (PMID 33557779, 2021). "Thereby, we have confirmed that IL-6 remains an excellent predictor and found that it represents a COVID-19 biomarker regardless the epidemic peak curves." (PMID 34675240, 2021). "In our study, IL-2R and IL-6 significantly decreased in the cancer patients who recovered from COVID-19." (PMID 33735106, 2021). "It has been shown that in patients with severe COVID-19 treatment with leronlimab reduces elevated plasma IL-6 and chemokine ligand 5 (CCL5), and normalized CD4/CD8 ratios." (PMID 33521616, 2021).
COVID-19 (continued). "The high percentage of CD14+CD16+ monocytes in severe COVID-19 patients have been demonstrated in two studies, which are specialized in producing inflammatory mediators including GM-CSF and IL-6, IL-10, and TNF-α." (PMID 33757410, 2021). "There is reason to assume that severely ill COVID-19 patients suffer from NTIS because IL-6 levels, which are generally increased in this condition, were identified as prognostic parameter for severity of COVID-19 infection." (PMID 33981284, 2021). "The cirrhosis-associated abnormalities of ACE, IL-6, VWF antigen, and antiplasmin parallel those observed in severe COVID-19." (PMID 34945736, 2021). "Inflammasome-derived products such as Casp1p20 and IL-18 in the sera were correlated with the markers of COVID-19 severity, including IL-6 and LDH." (PMID 33613573, 2021). "Detectable SARS-CoV-2 RNA in peripheral blood (RNAaemia) has been observed in critically ill COVID-19 patients with drastic increase in circulating IL-6 levels." (PMID 34379684, 2021). "Because higher levels of IL-6 have been associated with disease severity and serve as an indicator of poor outcomes, most of the mAbs under clinical investigations are IL-6 inhibitors intended for use in moderate-to-severe COVID-19 patients." (PMID 33714258, 2021). "Their study found statistically significant variation in values by the type of assay used for IL-6, IL-8, and TNF-α, which were the most implicated cytokines in the pathophysiology of COVID-19." (PMID 34358229, 2021). "The range in doses was chosen from data published on bLf efficacy against anemia of inflammation on hereditary thrombophilic pregnant women with high levels of serum IL-6 (100–200 mg two times a day) as well as on COVID-19 patients (200 mg five times a day)." (PMID 34575388, 2021). "Of these age-correlated proteins, six had been also associated with COVID-19 severity: HGF and CXCL9 shown the highest coefficients while IL10RB, VEGFA, IL-6 and TNF showed low albeit significant correlation (r < 0.30)." (PMID 34335580, 2021). "IL-6 was significantly higher in COVID-19 group as compared with non-COVID-19 group (76.10 ± 82.35 vs. 6.99 ± 3.99, 95% CI 52.18–100.01, P-value <0.01)." (PMID 33784355, 2021). "A recombinant humanized anti-IL-6 receptor monoclonal antibody (Tocilizumab) is being used for treating COVID-19 patients that inhibits the binding of IL-6 to both membrane and soluble IL-6 receptors, blocking IL-6 signaling and reducing inflammation." (PMID 34575353, 2021). "A recent study revealed that IL-6 levels were positively correlated with VAS scores in COVID-19 patients with headache." (PMID 34384355, 2021). "Serum IL-6 levels have been found to be significantly increased in critically ill patients; compared to moderate and severe COVID-19 cases, its levels show direct correlation to the disease severities." (PMID 33445810, 2021). "IL-6 itself can increase the severity of COVID-19 by up-regulating angiotensin-converting enzyme 2 receptor and inducing cathepsin L production in macrophages, thus mediating the cleavage of the S1 subunit of the coronavirus surface spike glycoprotein." (PMID 34578898, 2021). "A high IL-6/IFN ratio seems to predict high severity in COVID-19 as well as lung damage as a result of “cytokine storm”." (PMID 34946266, 2021). "Based on this evidence, the potential influential role of NETs and their by-products in COVID-19 pathogenesis and outcome is now rapidly gaining acceptance and has also been considered in treatment approaches in COVID-19 such as anti-IL6 and IL26 therapy." (PMID 34367376, 2021). "In spite of the recommendation by some medical societies against the initiation or continuation of bDMARDs (including anti-TNF drugs) in the places where COVID-19 has been circulating in the community, the use of anti-IL-6 agents has been regarded to be safer." (PMID 34943795, 2021).